INS (insulin)
Diseases named in the same sentence as INS in open-access papers (continued):
Sharing a sentence is not in itself a finding about the gene and the disease.
type 1 diabetes (continued). "Type I diabetes, known as insulin-dependent diabetes, is a chronic condition whereby the pancreas produces little or no insulin." (PMID 26221177, 2015). "A reduction in bone mass in Type 1 diabetes mellitus (T1DM) is generally accepted to be related to high fracture risk resulting from a lack of insulin; however, patients with T2DM often have normal or slightly high bone mineral density (BMD), suggesting impaired bone quality rather than quantity." (PMID 25872143, 2015). "Inhibition of glucagon secretion may be involved in the efficacy of DPP-4 inhibitors for insulin-treated patients and inhibition of glucagon secretion as a GLP-1 receptor agonist may be important in type 1 diabetes." (PMID 26124906, 2015). "When there is no local insulin production in type 1 diabetes, pancreas volume is known to be decreased by one third and this is evident within months of diagnosis." (PMID 25950180, 2015). "Type 1 diabetes is an autoimmune disease in which the β-cells in the Langerhans islands of the pancreas are destroyed, resulting in a lack of insulin." (PMID 26136751, 2015). "β cells are lacking in type 1 diabetes, while in type 2 diabetic patients, β cells cannot compensate for the increased insulin demand due to their reduced capacity to secrete insulin in response to high blood glucose." (PMID 25497096, 2014). "Failure or absence of insulin-producing cells as a result of the auto-immune destruction of β-cells in these islets leads to type I diabetes mellitus." (PMID 25526563, 2014). "All individuals with type 1 diabetes must receive insulin, and it is impossible to do so in Sweden without having been entered in the PDR." (PMID 24710965, 2014). "In type 1 diabetes, endogenous insulin levels are low to absent secondary to autoimmune beta cell destruction." (PMID 24668543, 2014). "Rarely, patients initially assumed to have Type 1 diabetes have managed to maintain euglycaemia without treatment and have stopped using insulin for longer than would be expected of the honeymoon period." (PMID 24909320, 2014). "Type 1 diabetes mellitus (T1DM) is an autoimmune disease in which β-cells are completely destroyed, resulting in metabolic dysfunction as a consequence of insufficient circulating levels of insulin." (PMID 25688339, 2014). "The prolonged length of time without insulin is not consistent with Type 1 diabetes in the honeymoon period." (PMID 24909320, 2014). "The recent SWITCH (Sensing with Insulin pump Therapy to Control HbA1c) study investigated the impact on metabolic control of combining CGM with CSII therapy in a mixed population of paediatric and adult patients with type 1 diabetes." (PMID 25037251, 2014). "Previous work has demonstrated that patients this many years after a diagnosis of Type 1 diabetes are unlikely to be producing endogenous insulin in such quantities." (PMID 24909320, 2014). "We have qualified our STZ model, as non-insulin dependent, but would not refer to as a type 2 model, since we believe it more closely resembles type 1 diabetes." (PMID 24410801, 2014). "In a sensitivity analysis, 59% of incident insulins only users among women aged 30–39 years in 2008 had stopped insulin treatment within the following two years, indicating gestational diabetes rather than Type 1 diabetes." (PMID 24886413, 2014). "Type 1 diabetes, also known as insulin-dependent diabetes, results from an absolute lack of insulin due to autoimmune destruction of the insulin-producing beta cells in the pancreas." (PMID 24818152, 2014). "When insulin-dependent and non-insulin-dependent diabetes and bisphosphonate use was examined, the results were not statistically significant prior to multiple imputation." (PMID 24919660, 2014). "Insulin deprivation decreased gene transcription of most adipokines in each fat depot except adiponectin and visfatin which were not affected in type 1 diabetes." (PMID 25170835, 2014).
type 1 diabetes (continued). "Reviewing some of the early studies also did not reveal the effects of physical activity on non-insulin dependent diabetes, fasting blood glucose, insulin level and glucose tolerance." (PMID 25560330, 2014). "A small study of 101 French general practitioners identified few (53%) would adjust insulin dosing for type 1 diabetes patients during Ramadan and most who would admitted not offering specific instructions to the patient." (PMID 24606885, 2014). "Consistent with the absolute requirement for insulin in type 1 diabetes, none of the subjects was able to discontinue insulin." (PMID 24668543, 2014). "Levine examined predictors of glycemic control in pediatric type 1 diabetes, but the study was performed prior to the use of basal insulin analogs and therefore did not address our primary question." (PMID 24653838, 2014). "It has been reported that insulin withdrawal for 8 h in patients with type 1 diabetes treated with CSII increased IGFBP1 concentrations sixfold, and it is conceivable that the high IGFBP1 values could be due to a lag in insulin delivery." (PMID 24327601, 2014). "Type 1 diabetes (T1D) is an autoimmune disease characterized by destruction of pancreatic β-cells and lack of endogenous insulin." (PMID 24878748, 2014). "Hospital admission for type 1 diabetes initial care, patient education and insulin management training in new-onset non-critically ill children did not result in better metabolic outcomes during the first year post-diagnosis and increased cost." (PMID 23587308, 2013). "To test whether the increased expression of PTEN after chronic GH treatment was involved in the interaction of GH with insulin, we conducted our test in STZ-induced type I diabetic mice." (PMID 23840818, 2013). "With the present lack of a successful therapeutic, the delivery of insulin secreting pancreatic islet cells (PICs) has proven promising for the treatment of type 1 diabetes." (PMID 26555963, 2013). "Type 1 diabetes is an autoimmune disease that destructs insulin-producing beta cells of the pancreas with subsequent lack of insulin and leads to increased blood and urine glucose." (PMID 23405067, 2013). "Recently, a randomized controlled trial in 310 pregnant women with type 1 diabetes demonstrated noninferiority of detemir versus NPH insulin in terms of maternal efficacy (HbA1c) and safety (hypoglycemia)." (PMID 23840206, 2013). "Type 1 diabetes occurs when the body produces no insulin because of autoimmune destruction of the pancreatic cells that normally produce it." (PMID 25100684, 2013). "It is important to emphasize that subject 1 has type 1 diabetes with irregular control of glycemia despite receiving insulin therapy and that subject 2 is non-diabetic." (PMID 24386337, 2013). "Absent C-peptide at any time confirms absolute insulin requirement and the appropriateness of Type 1 diabetes management strategies regardless of apparent aetiology." (PMID 23413806, 2013). "The spontaneous destruction of insulin producing pancreatic beta cells in non-obese diabetic (NOD) mice provides a valuable model of type 1 diabetes." (PMID 23418596, 2013). "All patients with type 1 diabetes, and some with type 2, must inject themselves regularly with insulin, but this does not always fully control the disease." (PMID 24252877, 2013). "Currently, there is no effective treatment strategy to restore endogenous insulin secretion in patients with type 1 diabetes." (PMID 23555060, 2013). "Particularly, in type 1 diabetes, the lack of insulin-secreting β-cells diminishes the suppressive effect of endogenous insulin on α-cell secretion." (PMID 23316165, 2012). "Current immune treatments for type 1 diabetes, such as immunosuppressants and anti-cytokines, are non-specific, killing or harming both the pathological T cells (i.e., insulin-autoreactive cytotoxic T cells) and healthy cells." (PMID 22905105, 2012).
type 1 diabetes (continued). "We aimed to explore the role of insulin sensitivity (Si) as an early factor of atherosclerosis in young type 1 diabetes vs. non-diabetic subjects." (PMID 23185996, 2012). "There was no detectable endogenous insulin content in the milk of mothers with type 1 diabetes; therefore, all insulin detected in the milk of mothers with type 1 diabetes was of exogenous origin." (PMID 22500167, 2012). "Mechanistically, during insulin therapy for type 1 diabetes, the exogenous level of insulin does not decrease in response to the lowering of blood glucose, due to a lack of endogenous glucose-sensing mechanisms." (PMID 23316165, 2012). "In the years subsequent to onset of type 1 diabetes, the beta cell mass slowly declines until there is no endogenous insulin production." (PMID 22973412, 2012). "Since it does not increase insulin levels, although it requires the presence of endogenous insulin, metformin can also be used in patients with type 1 diabetes, when they have residual functioning pancreatic β-cells." (PMID 22577575, 2012). "However, in a rodent model of type 1 diabetes, Bacillus Calmette-Guerin (BCG) reverses disease by restoring insulin secretion." (PMID 22905105, 2012). "In a minority (<10%) of patients, the need for insulin therapy continues after delivery, and in these cases detection of anti-glutamic-acid-decarboxylase- (GAD-) 65 antibodies (GAD65-Ab) is common, and so GDM is considered the onset of type 1 diabetes." (PMID 22654905, 2012). "The case was considered type 1 diabetes if there was at least one prescription for insulin within 120 days of the index date, with no more than a single prescription for an oral hypoglycemic in that interval." (PMID 22920280, 2012). "As it was noted previously, experimentally induced models of insulin-dependent diabetes are often not completely devoid of endogenous insulin." (PMID 22899950, 2012). "If the starvation period is short (only one missed meal), patients can be managed without intravenous insulin (even with type 1 diabetes)." (PMID 22943220, 2012). "We show that non-obese young adults with type 1 diabetes have early signs of atherosclerosis, as reflected by a significantly increased cIMT concomitant with lower insulin sensitivity, compared with matched non-diabetic individuals." (PMID 23185996, 2012). "C-peptide was identified in milk mothers with type 1 diabetes, but at 15 to 20x lower than reference blood concentrations, despite the common view that patients with type 1 diabetes do not produce insulin." (PMID 22500167, 2012). "Namely, Type 1 diabetes was induced by streptozotocin (STZ), a nitrosurea derivative isolated from Streptomyces achromogenes able to induce specific destruction of β-pancreatic cells in rats, thus representing a typical model of insulin dependence." (PMID 19887507, 2011). "As patients with type 1 diabetes have no/negligible endogenous insulin, the measurements of insulin, glucose and other metabolic effects are ascribed to the administration of exogenous insulin." (PMID 21410860, 2011). "Because patients with type 1 diabetes do not produce sufficient quantities of insulin, they are dependent on exogenous insulin to maintain blood glucose at normal levels." (PMID 21569626, 2011). "In fact, insulin-specific T-cells can be isolated from human subjects both in the prediabetic phase and the onset of type 1 diabetes and are present in the diabetes-prone non-obese diabetic (NOD) mouse, an animal model of the human disease." (PMID 21059249, 2010). "Type 1 diabetes is an autoimmune disease that is characterized by destruction of insulin-producing pancreatic β-cells, resulting in a lack of or even absence of insulin production and disturbed glucose homeostasis." (PMID 20585661, 2010). "Intranasal insulin could prevent cognitive decline and GSK3 activation in a mouse model of type I diabetes." (PMID 21044348, 2010).
type 1 diabetes (continued). "Type 1 diabetes (T1D) is an autoimmune disease characterized by the absence of insulin due to the specific destruction of the insulin-producing β cells of the pancreatic islets." (PMID 19799787, 2009). "The characteristics of type 1 diabetes are thepermanent lack of insulin production from the pancreas due to the destructionof the β cells of the Islets of Langerhans." (PMID 18437199, 2008). "Insulin is vital to patients with type 1 diabetes - they cannot live without a source of exogenous insulin." (PMID 21394262, 2008). "Diabetes type 1 was induced in other groups (by streptozotocin) and animals received insulin or vitamin E (300 mg /kg body weight), both insulin and vitamin E, or no treatment for 4 weeks according to their group." (PMID 18949102, 2008). "Imagine a 60-year old woman, with no education after her 16th birthday, type 1 diabetes requiring 50 units of insulin per day and an HbA1c-% of 8.0." (PMID 18823555, 2008). "In the presence of extremely high plasma insulin concentrations, as occur in overdose, glucose dynamics closely resemble those observed in healthy nondiabetic patients and type 1 diabetes during euglycaemic hyperinsulinaemic clamp (10 mU/kg per minute)." (PMID 17963523, 2007). "Insulin-dependent diabetes patients should perhaps also take into account the composition of the meal and its affects on the GER, as well as the carbohydrate content of the meal before the administration of short-acting insulin." (PMID 18093343, 2007). "A 25-year-old, with type I Diabetes Mellitus with a previous diagnosis of Protamine Allergy but not to human Insulin, started to notice anaphylactic reactions inmmediatly after bolus with Insulin." (PMID 16375762, 2005). "Insulin therapy should never be withheld in a patient with type 1 diabetes as this can result in DKA." (PMID 15916471, 2005). "Type 1 diabetes is characterized by the absence of insulin and is managed through balancing food intake, daily physical activity, and insulin injections." (PMID 16263044, 2005). "Once identified, families live with the knowledge that their child has an increased chance of developing symptomatic, lifelong, insulin-requiring type 1 diabetes but have no specific clinical pathway available to them in Western Australia (WA) for accessing tailored support or education." (PMID 41634173, 2026). "In type 1 diabetes mellitus (T1DM), low bone mineral density (BMD) is commonly observed due to the absence or reduction of insulin signaling in bone." (PMID 41566690, 2026). "Type 1 Diabetes (T1D) is an autoimmune condition where the body’s immune system mistakenly attacks and destroys insulin-producing beta cells in the pancreas, leading to little or no insulin production." (PMID 41596635, 2026). "Importantly, research trials on the amount and timing of prandial bolus insulin reductions before PA in children and adults with type 1 diabetes using Omnipod 5 are not currently available." (PMID 39653802, 2025). "The absence of insulin production or secretion is typically referred to as type 1 diabetes (T1D)." (PMID 40481412, 2025). "A case report from 2020 revealed some potential of fenofibrate by demonstrating maintained euglycaemia, without any insulin therapy, in a patient with newly diagnosed type 1 diabetes treated with a daily oral dose of fenofibrate initiated 7 days after diagnosis." (PMID 39477880, 2025). "However, it is more likely that these differences relate to the fact that our participants were treated with exogenous insulin injected subcutaneously whereas insulin in people without type 1 diabetes is of endogenous origin." (PMID 40531210, 2025). "The only differentiating factor of this case from the other type 1 diabetes cases was that it did not contain any ICIs, and this suggests that the increased presence of macrophages might be dependent on the presence of insulin." (PMID 41000615, 2025).
type 1 diabetes (continued). "Meanwhile, we hope to have shown that the closed-loop systems, rhetorically referred to as an “artificial pancreas,” are in fact simply a way -albeit a sophisticated one-of administering exogenous insulin, and are no more a cure for type 1 diabetes than dialysis is a cure for kidney failure." (PMID 40236755, 2025). "This study evaluated 6-month effectiveness and safety of automated insulin delivery (AID) in comparison with multiple daily injections (MDI) in pediatric and adult type 1 diabetes (T1D)." (PMID 41488135, 2025). "Timing is crucial in diseases like type 1 diabetes where complete elimination of insulin-producing pancreatic beta cells may not be reversed even after the elimination of autoreactive T/B-cells." (PMID 39379698, 2025). "The participants with type 1 diabetes might not be representative of the general population due to the requirement of insulin pump therapy." (PMID 38613227, 2025). "Insulin-dependent diabetes mellitus (IDDM) refers to a diabetic condition in which insulin therapy is required for patients who do not adequately respond to oral hypoglycemic agents, as well as for those who have developed microvascular or macrovascular complications." (PMID 41440956, 2025). "In type 1 diabetes, available data remain limited; however, the ONWARDS 6 and QWINT-5 trials demonstrated that once-weekly icodec and efsitora, respectively, achieved comparable reductions in HbA1c to once-daily insulin degludec, when used in combination with prandial insulin." (PMID 40937414, 2025). "The extract did not affect glucose tolerance or insulin levels in subjects with juvenile (type 1) diabetes, suggesting that the extract harbored an unknown hormone with insulinotropic actions." (PMID 40024571, 2025). "In the only study to assess differences in miRNA expression during insulin therapy in children with type 1 diabetes, 27 Australian adolescents without significant differences in baseline characteristics were randomized to CSII or MDI within 3 months of disease onset." (PMID 40989118, 2025). "Type 1 diabetes mellitus (T1DM) is a chronic condition in which the pancreas produces little or no insulin by itself—it is a complex autoimmune disease with genetic implications defined by T-cell-mediated destruction of pancreatic β cells leading to uncontrolled hyperglycemia and insulin dependence." (PMID 38397350, 2024). "In addition, HbA1c was 8.3%, no insulin secretion and negative antibodies characteristic for type 1 diabetes were found." (PMID 39766859, 2024). "Insulin treatment is crucial, especially for type 1 diabetes, due to the lack of β-cell function." (PMID 39065795, 2024). "Type 1 diabetes is characterized as a severe inadequacy or absence of releasing insulin by the pancreas due to an unknown disorder in the immune system, it affects people at a younger age more often, and it also can affect children." (PMID 39063417, 2024). "Poor acceptance of type 1 diabetes leads to non-compliance with insulin therapy." (PMID 39735069, 2024). "Unlike type 1 diabetes, which is autoimmune in nature, or type 2 diabetes, which is often associated with lifestyle factors, MODY is caused by mutations in specific genes involved in insulin production." (PMID 39310514, 2024). "Thus, it may be of therapeutic value to preserve beta cells across all clinical stages of type 1 diabetes progression, to mitigate the deterioration of beta cell morphology (i.e. size) and identity (i.e. insulin and PC1/3 co-localisation, and insulin content)." (PMID 39404844, 2024). "In type 1 diabetes, the pancreas produces little or no insulin." (PMID 38378741, 2024). "In type 1 diabetes (T1D), several autoantibodies against islet cell cytoplasmic proteins, glutamic acid decarboxylase (GAD-65), insulin and protein tyrosine phosphatases have been identified." (PMID 39658052, 2024). "For type 1 diabetes, UVR exposure may decrease the autoimmune attack on insulin-producing cells." (PMID 39744344, 2024).